RN7SKP1 (RN7SK pseudogene 1)
Gene: Miscellaneous RNA gene on chromosome 13 (37,166,352 to 37,166,658, reverse strand). Ensembl gene ENSG00000202395.
Homologues: Orthologues: mouse Gm55840 (59% identical), guinea pig 7SK (45% identical). Paralogues in human: 7SK (79% identical), RN7SKP204 (77% identical), RN7SKP176 (77% identical), RN7SKP180 (76% identical), RN7SKP203 (76% identical), RN7SKP90 (76% identical), RN7SKP71 (75% identical), RN7SKP118 (75% identical), RN7SKP255 (75% identical), RN7SKP9 (75% identical), RN7SKP184 (75% identical), RN7SKP217 (75% identical), and 284 more.